EZR (ezrin)
Diseases named in the same sentence as EZR in open-access papers (continued):
Sharing a sentence is not in itself a finding about the gene and the disease.
gastric cancer (14 papers, 2006 to 2025). A primary or metastatic malignant neoplasm involving the stomach. "Specifically, Ezrin can be used as an early diagnostic marker and to predict later metastasis in gastric cancer using meta-analysis." (PMID 33240887, 2020). "First, the pooled data of 6 studies showed that high Ezrin expression was significantly associated with tumor grade in gastric cancer (OR = 2.32, 95% CI = 1.53–3.52, P = 0.000)." (PMID 29190988, 2017). "For gastric cancer, Ezrin expression was associated with tumor grade (OR 2.32, 95% CI 1.53–3.52), TNM stage (OR 4.69, 95% CI 1.38–15.89), lymph node involvement (OR 3.96, 95% CI 1.47–10.70) and overall survival (HR 1.88, 95% CI 1.33–2.66)." (PMID 29190988, 2017). "Furthermore, increased EZR expression is related to Helicobacter pylori infection, a risk factor for gastric cancer." (PMID 38972247, 2024). "We also found that high Ezrin expression was significantly associated with OS in gastric cancer." (PMID 29190988, 2017). "Second, the pooled data from 4 studies showed that high Ezrin expression was significantly associated with the TNM stage of gastric cancer (OR = 4.69, 95% CI = 1.38–15.89, P = 0.013), but the heterogeneity among these 4 studies was significant (I2 = 90.6%, P = 0.000)." (PMID 29190988, 2017). "In summary, this study reveals elevated EZR expression in cervical and gastric carcinoma, highlighting its potential as a molecular target for treating these cancers." (PMID 38972247, 2024). "Succinylation is reported to occur on ezrin Lys60, and a global proteome analysis for human gastric cancers also identified Lys438 in ezrin, human radixin Lys435, mouse radixin Lys83, and moesin Lys79 and Lys165." (PMID 31018575, 2019). "Our results showed significant association between high Ezrin expression and multiple clinical parameters including tumor grade, TNM stage and lymph node metastasis in gastric cancer." (PMID 29190988, 2017). "The relationship between Ezrin expression and the clinicopathological features of gastric cancers was analyzed." (PMID 23039327, 2012). "The high frequency of Ezrin expression suggests a central role in gastric cancer biology, though the further study needs to be investigated for exploring the mechanism in detail." (PMID 23039327, 2012). "Consistently, strong expression of Ezrin was significantly correlated with poor prognosis of gastric cancer." (PMID 23039327, 2012). "In the present study, higher strongly expression rate of Ezrin protein was detected in intestinal type (65.8%) and diffuse type (61.2%) of gastric cancer than that in the mixed type (28.6%) cases." (PMID 23039327, 2012). "The present findings provide promising evidence that ezrin may be a molecular target in the treatment of cervical and gastric carcinoma." (PMID 38972247, 2024). "miR-183 antagonizes Ezrin and acts as a tumor suppressor in gastric cancer." (PMID 33240887, 2020). "Decreased miR-183 and elevated Ezrin have been reported in gastric cancer cells and tissues." (PMID 33240887, 2020). "The Ezrin protein is up-regulated in gastric cancer lesions." (PMID 33240887, 2020). "The pooled data of two studies showed that high Ezrin expression was significantly associated with overall survival (OS) for gastric cancer (HR = 1.88, 95% CI = 1.33–2.66, P = 0.000), and no significant heterogeneity was observed (I2 = 0.0%, P = 0.446)." (PMID 29190988, 2017). "For gastric cancers, Ezrin is useful in predicting distant metastasis." (PMID 29190988, 2017). "There were 7 studies with data on Ezrin expression and gastric cancer." (PMID 29190988, 2017). "Similarly, Lauren intestinal (65.8%, 77/117) and diffuse (61.2%, 85/139) types of gastric cancer also determined strongly expression rate of Ezrin protein compared to the mixed type (28.6%, 6/21) cases (P < 0.05)." (PMID 23039327, 2012). "All above data strongly indicated that Ezrin could be regarded as a potential prognostic factor in gastric cancers." (PMID 23039327, 2012).
gastric cancer (continued). "Ezrin protein located in the cytoplasm and/or membrane in the migrating gastric cancer cells, and it mainly concentrated at the protrusion site; however, only cytoplasmic distribution was observed in the non-migrating cancer cells by immunofluorescence staining." (PMID 23039327, 2012). "There is accumulating evidence suggesting that Ezrin is a metastatic determinant and a key component in tumor metastasis, however, its exact role in gastric cancer is still unknown." (PMID 23039327, 2012). "In present study, we therefore aimed to investigate the Ezrin protein expression in human gastric adenocarcinoma and its precancerous lesions, and to explore the exactly relation of Ezrin expression to the clinical outcomes and the histological parameters of gastric cancers." (PMID 23039327, 2012). "Limited reports suggest that Ezrin may be a useful prognostic and survival indicator for gastric cancers." (PMID 23039327, 2012). "It means that Ezrin could be a potential biomarker for predicting prognosis in gastric cancer." (PMID 29190988, 2017). "Respectively, 6/4/6/3 studies had data regarding Ezrin expression and tumor grade/TNM stage/lymph node involvement/distant metastasis in gastric cancer." (PMID 29190988, 2017). "Our results demonstrate significantly greater expression of fascin-1, ezrin and paxillin in LSCC than ANM tissues, which agrees with observations in ESCC, gastric cancer, and NSCLC." (PMID 23209815, 2012). "In addition, a gastric cancer cell line, MKN-1, was also used for immunofluorescence staining to evaluate the distribution of Ezrin protein." (PMID 23039327, 2012). "For the tissue sections, diffusely and strongly positive signals for Ezrin protein was detected in the cytoplasm of gastric cancer cells, however negative or scattered positive cells, mainly basal reserve cells, was observed in the normal gastric epithelia by immunohistochemistry." (PMID 23039327, 2012). "However, apical localization of Ezrin protein was seen neither in gastric carcinoma nor in normal gastric epithelia by immunohistochemistry." (PMID 23039327, 2012). "But Ezrin protein expression level was not correlated with the patient age, gender, WHO’s histological type status of gastric carcinomas (P>0.05)." (PMID 23039327, 2012).
esophageal squamous cell carcinoma (13 papers, 2013 to 2025). Esophageal squamous cell carcinoma (ESCC) is a type of esophageal carcinoma (EC) that can affect any part of the esophagus, but is usually located in the upper or middle third. "In esophageal squamous cell carcinoma (ESCC), Ezrin activation and E-cadherin absence were observed to contribute to tumorigenesis and metastasis, where Ezrin and E-cadherin expression is negatively associated." (PMID 37371090, 2023). "The present study aimed to investigate the expression of DRP-1 (a member of the DAPK family), ezrin and E-cadherin in esophageal squamous cell carcinoma (ESCC), and to analyze their association with clinicopathological factors in order to explore their potential in ESCC diagnosis." (PMID 24959233, 2014). "The aim of this study was to analyze the role of Ezrin in esophageal squamous cell carcinoma (ESCC) and investigate potential therapeutic targets for ESCC by interfering with Ezrin expression." (PMID 37791063, 2023). "The important biological role of Ezrin in human esophageal squamous cell carcinoma (ESCC) has been revealed in our previous studies." (PMID 25126570, 2014). "Ezrin, coding protein EZR which cross-links actin filaments, overexpresses and involves invasion, metastasis, and poor prognosis in various cancers including esophageal squamous cell carcinoma (ESCC)." (PMID 25126570, 2014). "We previously showed that the overexpression of ezrin in esophageal squamous cell carcinoma (ESCC) may be involved in the growth and invasiveness of ESCC cells and ezrin expression can serve as a biomarker that predicts the prognosis of ESCC patients." (PMID 25915860, 2015). "Ezrin silencing downregulates the MAPK and TGF-β pathways in esophageal SCC." (PMID 23357878, 2013). "In addition, the phosphorylation of ERK was reduced in ezrin‐KD cells, and activation of the ERK/MAPK pathway may partially attenuate the Ezrin‐mediated suppression of cell invasiveness in esophageal SCC." (PMID 32281236, 2020).
non-small cell lung carcinoma (12 papers, 2013 to 2025). A group of at least three distinct histological types of lung cancer, including non-small cell squamous cell carcinoma, adenocarcinoma, and large cell carcinoma. "The role of actin-binding proteins, including profiling, fascin, and ezrin, in the metastasis of non-small cell lung cancer (NSCLC)." (PMID 38609844, 2024). "Runx2 and Ezrin expressions are closely correlative to postoperative recurrence and metastasis in patients with non-small cell lung cancer." (PMID 31331331, 2019). "In addition, S-nitrosylation of ezrin has been shown to mediate non-small-cell lung cancer invasion and metastasis." (PMID 34198671, 2021). "This study investigated the prognostic implications of ezrin and phosphorylated ezrin (p-ezrin) expression in non-small cell lung carcinoma (NSCLC)." (PMID 24629131, 2014).
tongue cancer (12 papers, 2013 to 2023). A malignant neoplasm affecting the tongue. "For instance, KCNQ1OT1 caused the alternation of tongue cancer proliferation and cisplatin resistance by modulating the miR-211-5p-mediated Ezrin/Fak/Src signaling pathway." (PMID 34335862, 2021). "For example, lncRNA KCNQ1OT1 regulates proliferation and cisplatin resistance in tongue cancer via miR-211-5p mediated Ezrin/Fak/Src signaling." (PMID 37875515, 2023). "Overexpression miR-211 significantly decreases cell cisplatin resistance in tongue cancer via targeting Ezrin/Fak/Src signaling." (PMID 35912006, 2022). "Overexpressed miR-211 significantly decreases cell proliferation in tongue cancer via targeting Ezrin/Fak/Src signaling." (PMID 35912006, 2022). "LncRNA KCNQ1OT1 regulates cisplatin resistance in tongue cancer via miR-211-5p-mediated Ezrin/Fak/Src signaling." (PMID 35311096, 2022). "LncRNA KCNQ1OT1 facilitates proliferation and chemo-resistance in tongue cancer by acting as a sponge of miR-211 through Ezrin/Fak/Src signaling." (PMID 35912006, 2022). "The lncRNA KCNQ1OT1 acts via miR-211–5p and downstream Ezrin/Fak/Src signaling to promote tumor growth and cisplatin resistance in tongue cancer." (PMID 34868237, 2021). "Many studies have reported that ezrin, ERK, STAT3, and AKT are associated with the development of tongue cancer cells and with the prognosis of patients with OTSCC." (PMID 32281236, 2020). "Moreover, LncRNA KCNQ1OT1 has been proved could regulate tongue cancer cell proliferation and cisplatin resistance via miR-211-5p mediated Ezrin/Fak/Src signaling." (PMID 35443864, 2022). "This suggests that ezrin may be a potential target for the treatment of human tongue cancers." (PMID 23357878, 2013). "We previously reported that ezrin is overexpressed in OTSCC and plays a vital role in tongue cancer cell growth, migration, and invasiveness via the E‐cadherin/b‐catenin complex and cadherin switch." (PMID 32281236, 2020). "Ezrin, ERK, STAT3, and AKT are proteins that are overexpressed in various types of cancer, although their expressions in tongue cancer has received less focus." (PMID 32281236, 2020). "We suppressed the expression of ezrin and ERK and evaluated the changes in cancer cell behaviour and morphology, particularly invadopodia formation, by culturing tongue cancer cell lines in a novel 3D system using CellbedTM." (PMID 30344309, 2018). "To screen for additional treatment targets against tongue cancer, we evaluated the contributions of extracellular signal-related kinase (ERK), AKT and ezrin in cancer development." (PMID 30344309, 2018).
glioblastoma (11 papers, 2018 to 2024). The most malignant astrocytic tumor (WHO grade IV). "One such study found that NFIX promotes glioblastoma cell migration by directly upregulating the expression of EZR (encoding ezrin), which is involved in linking the actin cytoskeleton and the plasma membrane and plays a role in cell migration." (PMID 36901722, 2023). "In glioblastoma, Ezrin interacts with and delocalizes the cytoskeletal-related protein neurofibromatosis type 2 (NF2), which carries out opposite activities in tumor growth." (PMID 33240887, 2020). "In biopsy specimens from 115 cases, ranging from WHO grade I pilocytic astrocytoma to WHO grade IV glioblastoma multiforme, a significant correlation of ezrin staining intensity with increasing malignancy of astrocytic tumours was found." (PMID 31382374, 2019). "A potential interaction between ezrin and the transcription factor Sox2 may be relevant for the sensitivity of glioblastoma cells to ionising radiation." (PMID 31382374, 2019). "In glioblastoma, this system is skewed towards ezrin activation." (PMID 31382374, 2019). "Thus, ezrin overexpression promotes a migratory phenotype of glioblastoma." (PMID 31382374, 2019). "With glioblastoma tissue that has an overexpression of both NF2 and Ezrin, Ezrin can inhibit Rac1 inhibition, leading to proliferation." (PMID 39796693, 2024). "We demonstrate that RNA isolated from pseudopodia of hGCs contains migration-specific transcripts including Cdc42, Cofilin-1, Ezrin, Ilk, Limk, STAT3, MMP2, and Itgb1, recently described as part of intracellular pathways related to glioblastoma migration." (PMID 30353164, 2019). "In addition, many partners, such as solute carrier family 34 member 2 (SLC34A2), cluster of differentiation 74 (CD74), fused in glioblastoma, Syndecan 4 (SDC4) and Ezrin (EZR), are rearranged with ROS1 in NSCLC." (PMID 35628598, 2022). "The direct influence of ezrin or PKCε on microvascular proliferation in glioblastoma has not yet been studied." (PMID 31382374, 2019). "One member of the ERM family of proteins, moesin, was reported overexpressed in glioblastoma (GBM), but two other ERM proteins, ezrin and radixin, show no significant differential expression, and knockdown of moesin alone reduced the migration of GBM cells." (PMID 29416017, 2018). "Notability, Ezrin, in a complex with NF2, enhances glioblastoma growth independent of its molecular conformation or subcellular localization." (PMID 33240887, 2020).
breast tumors (10 papers, 2010 to 2024). "Here, we demonstrate that ezrin phosphorylated at T567 is highly overexpressed in the membrane of human breast tumors and positively associated with invasive growth and HER2 overexpression." (PMID 24086451, 2013). "In late stage IIIB large tumors, ezrin was almost exclusively confined to a diffuse cytoplasmic distribution with little evidence for membrane association or perinuclear localization in virtually all of the breast tumors." (PMID 24182314, 2013). "Total ezrin protein levels showed an average of 4-fold increase in breast tumors compared to matched benign ductal tissues." (PMID 30678714, 2019). "Ezrin gene (EZR) expression was also significantly elevated in breast tumor compared with benign tissues." (PMID 30678714, 2019). "Src and ezrin exhibited a strong apical staining in breast ductal epithelium and diffuse cytoplasmic staining in the breast tumour." (PMID 25231728, 2014). "In early stage IA breast tumors, ezrin intracellular distribution localized with a strong perinuclear pattern and weak cytoplasmic and membrane staining." (PMID 24182314, 2013). "Here we observe, in a series of breast tumors, that while total ezrin changes its localization with progression, p-ezrin remains membrane bound and increases it expression such that it is highly overexpressed in tumors." (PMID 24086451, 2013). "Similar to the ERM protein family (i.e., ezrin and moesin), RhoA, RhoB and Cdc42 immunoreactivity was also observed in the stromal compartment of the breast tumour samples and its blood vessels." (PMID 23420497, 2013). "Importantly, Casey and colleagues demonstrated that a podocalyxin–ezrin complex increases breast tumor motility." (PMID 26796961, 2016). "Furthermore, high expression of ezrin in human breast tumours significantly correlated with elevated Src expression and the presence of lymphovascular invasion." (PMID 25231728, 2014). "We first asked whether total and phospho-ezrin are overexpressed in human breast tumors and how their relative localization may change with progression." (PMID 24086451, 2013). "Here, we observe that p(T567) ezrin is overexpressed in the membrane in aggressive human breast tumors and in the invadopodia in invasive breast cancer cells where it forms protein-protein signaling complexes with NHE1, ß1-integrin, EGFR and phosphorylated NHERF1." (PMID 24086451, 2013). "Therefore the AC2M2 cell line model is ideally suited for studying regulation of malignant breast tumor progression by phosphorylatable Y477 ezrin." (PMID 22397367, 2012). "CCR7, EZR, IDH2 and MMP9 were highly expressed in breast tumor tissues, whereas they were expressed at low levels in normal breast tissues (p < 0.001)." (PMID 38438469, 2024). "The results showed that CCL5 and IDH2 were not significantly differentially methylated in BRCA, while CCR7, EZR, IL8, and IL2RG were hypermethylated in normal tissues, and FLT3, MAPK10, and MMP9 were hypermethylated in breast tumor tissues." (PMID 38438469, 2024). "To do so, we had to deal with the fact that CCND1 in lung and breast tumour cell lines, EZR (Ezrin) and HMGB1 in normal Schwann cells, were the only published nuclear targets of ErbB3." (PMID 27191720, 2016). "Primary breast tumour cores from a nested cohort of a 63-patient TMA were assessed for total Src and ezrin expression using an IF-based AQUA." (PMID 25231728, 2014).
endometrial cancer (10 papers, 2011 to 2024). Primary or metastatic malignant neoplasm involving the endometrium (mucous membrane that lines the endometrial cavity). "We find that human low-grade endometrial cancers are associated with disrupted localization of the apical polarity protein Par3 and Ezrin while, the adhesion molecule E-cadherin remains unchanged, accompanied by decreased Notch signaling, and altered Notch receptor localization." (PMID 29206870, 2017). "In stage I endometrial cancers, ezrin expression was also linked to poorer prognosis." (PMID 23785665, 2013). "S100P influences cell invasion by interacting with Ezrin and reconstructing F-actin, which implies its involvement in the occurrence and development of endometrial cancer." (PMID 32883230, 2020). "S100P was mainly distributed in the cytoplasm and co-localized with Ezrin in endometrial cancer cells." (PMID 32883230, 2020). "Our laser confocal microscopy results showed the co-localized expression of S100P and EZRIN in endometrial cancer cells, which indicated that S100P might interact with Ezrin during the occurrence and progress of endometrial cancer." (PMID 32883230, 2020). "Our data show that signaling through deregulated integrin and tetraspanins may account for the observed increased expression of focal adhesion kinase (FAK) and ezrin in this endometrial cancer data set." (PMID 23785665, 2013). "All these results suggest that ezrin plays an important role in the pathological development of gynecological diseases, such as PCOS, endometriosis, recurrent miscarriage, endometrial cancer and other gynecological tumors." (PMID 36968198, 2023). "We next examined Ezrin and Par3 localization in G1 EEC (1B’, 1E and 1E’) and G2 EEC (1C’, 1F and 1F’) endometrial cancer samples." (PMID 29206870, 2017). "In this study, DOCK1 could promote the migration and invasion of endometrial cancer cells through decreasing E-cadherin expression and upregulating MMP9 and Ezrin expressions." (PMID 38438882, 2024).